ANXA3 (annexin A3)
Diseases named in the same sentence as ANXA3 in open-access papers (continued):
Sharing a sentence is not in itself a finding about the gene and the disease.
tumor (continued). "The protein ANXA3, regardless of heterogeneity was found to have increased expression in NF2−/− tumours and showed promising results for personalised therapy driving attention to the development of a specific inhibitor that could support the treatment of patients with NF2−/− tumours." (PMID 40562609, 2025).
cardiovascular disease (3 papers, 2023 to 2025). "The consistent expression patterns of ANXA3 and SOCS3 in AMI and other cardiovascular diseases emphasize their universality and reliability." (PMID 40760666, 2025).
infection (3 papers, 2018 to 2024). The state of being infected such as from the introduction of a foreign agent such as serum, vaccine, antigenic substance or organism. "We found that the abundance of ANXA3 transcripts was increased at much higher levels in response to plasma from patients who eventually died from the infection than in response to plasma from those who recovered." (PMID 32682335, 2020). "Specifically, the role that ANXA3 may play in enhancing pathogen clearance and prolonging survival of neutrophils could be beneficial during the early phase of the immune response to the infection." (PMID 32682335, 2020). "Four genes previously thought to influence the severity of Guillan–Barré syndrome (GBS) were affected differently but moderately (PTGS2, Fc.: 1.188×; ANXA3, Fc.: 1.31×; CREB1, Fc.: 1.73×) by the 3rd hour of infection." (PMID 38787238, 2024).
bacterial infection (2 papers, 2017 to 2024). "ANXA3 has also been identified in phagosome upon bacterial infection, likely involving its calcium and phospholipid biding ability." (PMID 28771541, 2017). "BacSig was defined as the signature of the host response to bacterial infection using the average expression of five representative genes, including S100A12, CD177, HP, ANXA3, and ARG1." (PMID 38790931, 2024).
metabolic disease (1 paper, 2023). A congenital disorder (due to inherited enzyme abnormality) or acquired (due to failure of a metabolically important organ) disorder resulting from an abnormal metabolic process. "Annexin A3 (ANXA3) plays crucial roles in cell migration and differentiation, inflammation, cardiovascular and membrane metabolic diseases." (PMID 36865686, 2023).
psychiatric disorder (1 paper, 2025). A disorder characterized by behavioral and/or psychological abnormalities, often accompanied by physical symptoms. "Our findings are consistent with those of previous studies investigating ANXA3 alterations in patients with psychiatric disorders." (PMID 41010398, 2025).
retinopathy (1 paper, 2016). "Studies performed with whole retinal sample collections describe a contribution of Anxa2 and Anxa3 in neovascularization neonatal models of oxygen-induced retinopathy where they were significantly up-regulated." (PMID 26324419, 2016).
ANXA3 also shares sentences with these, for which no sentence is quoted: systemic lupus erythematosus (3 papers); allergies (2); Cluster headache (2); colorectal adenocarcinoma (2); gastric tumor (2); non-small cell lung carcinoma (2); viral infection (2); acute renal failure (1); aortic aneurysm (1); Arthritis (1); autoimmune conditions (1); bipolar disorder (1); cerebral small vessel disease (1); colorectal (1); coronary artery disease (1); emphysema (1); endothelial dysfunction (1); gangrene (1); Graves disease (1); Hematuria (1); Hernia (1); Hutchinson-Gilford progeria (1); hyperopia (1); influenza (1); liver fibrosis (1); lung diseases (1); lupus nephritis (1); melanoma (1); meningitis (1); metastasis (1).
A further 14 diseases each share a sentence with ANXA3 in 1 paper.